C6orf136 (chromosome 6 open reading frame 136)
Synonyms: Em:AB023049.8
Tractability: PROTAC: ubiquitination databases record sites on it.
Gene: Protein-coding gene on chromosome 6 (30,647,033 to 30,653,210, forward strand). Ensembl gene ENSG00000204564.
Genetic constraint (gnomAD): Loss-of-function variants: 29 observed, 43.09 expected, observed/expected ratio (o/e) 0.67, 90% interval 0.5 to 0.92. The upper end of that interval is the gene's LOEUF score, 0.92, which puts it in group 3 of 6, group 1 being the genes least tolerant of losing a copy. Missense variants: 628 observed, 658.79 expected, observed/expected ratio (o/e) 0.95, 90% interval 0.89 to 1.02. Synonymous variants: 293 observed, 270.33 expected, observed/expected ratio (o/e) 1.08, 90% interval 0.98 to 1.19.
Homologues: Orthologues: chimpanzee C6H6orf136 (99% identical), macaque ATAT1 (92% identical), pig C6orf136 (53% identical), dog C6orf136 (52% identical), rabbit C6orf136 (51% identical), guinea pig C6orf136 (47% identical), mouse 2310061I04Rik (47% identical), rat 2310061I04Rik (46% identical), zebrafish si:ch211-215a10.4 (24% identical), tropical clawed frog c8h6orf136 (23% identical), Drosophila melanogaster CG16787 (13% identical), Caenorhabditis elegans C27B7.2 (8% identical).
Diseases named in the same sentence as C6orf136 in open-access papers:
C6orf136 is named in the same sentence as 5 diseases in open-access papers, as found by Europe PMC text mining. Sharing a sentence is not in itself a finding about the gene and the disease. The quoted sentences say what the papers report.
bladder cancer (2 papers, 2020 to 2023). "Moreover, C6orf136 was reported to be a core gene in a signature, which was identified as a novel biomarker for bladder cancer." (PMID 36894917, 2023). "Results from overall survival analysis and disease free analysis with clinical data from TCGA revealed that core mRNAs in the coexpression networks, AHCY, C6orf136 and LRIG1, correlate with the progression and recurrence of bladder cancer significantly." (PMID 32065779, 2020). "Notably, as core genes in the networks, AHCY, C6orf136 and LRIG1 show high potential to be prognosticators for bladder cancer." (PMID 32065779, 2020).
head and neck squamous cell carcinoma (2 papers, 2023 to 2024). A squamous cell carcinoma that arises from any of the following anatomic sites: lip and oral cavity, nasal cavity, paranasal sinuses, pharynx, larynx, and salivary glands. "Up to now, there is a little bit of understanding of C6orf136, which has only been reported in head and neck squamous cell carcinoma and pancreatic adenocarcinoma." (PMID 39609718, 2024). "C6orf136 is a conserved gene, which is hypermethylated responding to oncogene FOXM1 expression in head neck squamous cell carcinoma tissue cells." (PMID 36894917, 2023).
septic shock (1 paper, 2024). Shock caused by infection; frequently caused by gram negative bacteria, although some cases have been caused by other bacteria, viruses, fungi, and protozoa; characterized by fever, chills, tachycardia, tachypnea, and hypotension. "In this study, we recognized four immune-mitochondrial key genes (PGS1, C6orf136, THEM4, and EPHX2) in septic shock and designed a novel gene diagnosis model that provided a new and meaningful way for the diagnosis of septic shock." (PMID 39609718, 2024).
cancer (3 papers, 2019 to 2022). A tumor composed of atypical neoplastic, often pleomorphic cells that invade other tissues. "Lack of previous reports on the functions of C6orf136, further studies are needed to clarify cancer associated functions of this gene." (PMID 32065779, 2020).
C6orf136 also shares sentences with these, for which no sentence is quoted: pancreatic adenocarcinoma (1 paper).